E2F8 (E2F transcription factor 8)
Description:
Atypical E2F transcription factor that participates in various processes such as angiogenesis and polyploidization of specialized cells. Mainly acts as a transcription repressor that binds DNA independently of DP proteins and specifically recognizes the E2 recognition site 5'-TTTC[CG]CGC-3'. Plays a key role in polyploidization of cells in placenta and liver by regulating the endocycle, probably by repressing genes promoting cytokinesis and antagonizing action of classical E2F proteins (E2F1, E2F2 and/or E2F3). Required for placental development by promoting polyploidization of trophoblast giant cells. Acts as a promoter of sprouting angiogenesis, possibly by acting as a transcription activator: associates with HIF1A, recognizes and binds the VEGFA promoter, which is different from canonical E2 recognition site, and activates expression of the VEGFA gene.
Synonyms: E2F-8; FLJ23311
Tractability: PROTAC: ubiquitination databases record sites on it. Other modalities: a drug acting on it is in phase 2 or 3 trials.
Gene: Protein-coding gene on chromosome 11 (19,224,063 to 19,241,684, reverse strand). Ensembl gene ENSG00000129173.
Subcellular location: Nucleus
Subcellular location (Human Protein Atlas): Nucleoli; Nucleoplasm; Cytosol
Gene Ontology:
Molecular function: cis-regulatory region sequence-specific DNA binding; DNA-binding transcription factor activity; DNA-binding transcription repressor activity, RNA polymerase II-specific; protein binding; RNA polymerase II cis-regulatory region sequence-specific DNA binding; sequence-specific double-stranded DNA binding; DNA-binding transcription factor activity, RNA polymerase II-specific; DNA-binding transcription repressor activity; DNA binding; identical protein binding
Biological process: negative regulation of transcription by RNA polymerase II; positive regulation of transcription by RNA polymerase II; sprouting angiogenesis; cell cycle comprising mitosis without cytokinesis; chorionic trophoblast cell differentiation; hepatocyte differentiation; negative regulation of cytokinesis; placenta development; positive regulation of DNA endoreduplication; regulation of transcription by RNA polymerase II; trophoblast giant cell differentiation; regulation of DNA-templated transcription
Cellular component: nucleolus; nucleoplasm; chromatin; RNA polymerase II transcription regulator complex; nucleus; transcription regulator complex
Genetic constraint (gnomAD): Loss-of-function variants: 33 observed, 81.93 expected, observed/expected ratio (o/e) 0.4, 90% interval 0.3 to 0.54. The upper end of that interval is the gene's LOEUF score, 0.54, which puts it in group 2 of 6, group 1 being the genes least tolerant of losing a copy. Missense variants: 967 observed, 1,108 expected, observed/expected ratio (o/e) 0.87, 90% interval 0.83 to 0.92. Synonymous variants: 386 observed, 415.82 expected, observed/expected ratio (o/e) 0.93, 90% interval 0.85 to 1.01.
Homologues: Orthologues: chimpanzee E2F8 (99% identical), macaque E2F8 (97% identical), pig E2F8 (90% identical), dog E2F8 (90% identical), rabbit E2F8 (89% identical), guinea pig E2F8 (86% identical), rat E2f8 (84% identical), mouse E2f8 (83% identical), tropical clawed frog e2f8 (45% identical), zebrafish e2f8 (43% identical). Paralogues in human: E2F7 (36% identical), E2F2 (11% identical), E2F4 (11% identical), E2F3 (10% identical), E2F1 (9% identical), E2F5 (9% identical), E2F6 (7% identical).
Diseases named in the same sentence as E2F8 in open-access papers:
E2F8 is named in the same sentence as 77 diseases in open-access papers, as found by Europe PMC text mining. Sharing a sentence is not in itself a finding about the gene and the disease. The quoted sentences say what the papers report.
breast carcinoma (26 papers, 2014 to 2025). "Because of the specificity of E2F8 in basal-like breast cancer, in further studying the regulation of pathway networks by E2F8, we analyzed the signaling pathway networks associated with E2F8 using the GSCALite online tool and the STRING database." (PMID 36814821, 2023). "For example, it was shown that expression of E2F8 is associated with tumor progression in breast cancer, human hepatocellular carcinoma and lung cancer." (PMID 37492373, 2023). "E2F8 deficiency contributed to the suppression of cell migration and invasion in basal-like breast cancer." (PMID 36814821, 2023). "Based on these findings, we hypothesized that E2F8 could be used as an underlying target in basal-like breast cancer treatment." (PMID 36814821, 2023). "E2F8 is still poorly characterized in the context of brain tumors but it has been implicated in the development of various cancer types including lung cancer, lymphoma, colon cancer, cholangiocarcinoma, prostate cancer, hepatocellular carcinoma and breast cancer." (PMID 33804958, 2021). "E2F8 has been associated with CDK4/6 inhibitor resistance, is overexpressed in patients with breast cancer, and has been significantly correlated with poor patient survival and cancer progression." (PMID 39057065, 2024). "E2F8 has been suggested as a marker of breast relapse-free survival and distant metastasis-free survival in breast cancer patients." (PMID 39057065, 2024). "As such, we believe that the role of E2F8 as a mechanistic marker, specifically in aromatase-resistant breast cancer, warrants further exploration." (PMID 39057065, 2024). "In breast cancer, the combination of E2F8 and hypoxia-inducible factor 1 (HIF1) has been shown to promote angiogenesis by inducing the expression of vascular endothelial growth factor A (VEGFA)." (PMID 36814821, 2023). "Next, the immune expression signatures between E2F8 and breast cancer were identified by TISIDB online." (PMID 36814821, 2023). "To uncover the oncogenic feature of E2F8 in basal-like breast cancer, we knocked down E2F8 expression using small interfering ribonucleic acid (siRNA) in MDA-MB-231 and BT20 cell lines." (PMID 36814821, 2023). "The cell cycle was significantly accelerated, and the hormone estrogen receptor pathway was repressed by E2F8 in breast cancers." (PMID 36814821, 2023). "For example, human E2F7 promotes proliferation and inhibits differentiation of acute myeloid leukemia cells and E2F8 overexpression promotes proliferation and tumorigenicity in breast cancer cell lines." (PMID 36063055, 2022). "As a downstream target of YTHDF1-METTL14, E2F8 was first identified to be involved in DNA damage repair and chemoresistance in breast cancer." (PMID 35279688, 2022). "In particular, recent literature has shown that the expression of E2F8 is noticeably enhanced in multiple carcinomas, including lung cancer, breast cancer, and hepatocellular carcinoma, implying that E2F8 is involved in oncogenesis and cancer progression." (PMID 32823614, 2020). "E2F8 has been reported to overexpress in lung cancer, breast cancer, colorectal cancer, ovarian cancer, prostate cancer, esophageal squamous cell carcinoma and HCC." (PMID 31990034, 2020). "E2F8 promotes cell proliferation and tumorigenicity in breast cancer and cisplatin resistance to estrogen receptor positive breast cancer cells." (PMID 31238586, 2019). "Collectively, these results further support the notion that upregulation of E2F8 contributes to uncontrolled cell proliferation and tumorigenecity, resulting in poor clinical outcome in breast cancer." (PMID 26992224, 2016). "Taken together, these data suggest that E2F8 plays important roles to promote breast cancer cell proliferation and colony formation in vitro." (PMID 26992224, 2016).
breast carcinoma (continued). "E2F8, a novel identified E2F family member, was found to be associated with the progression of several human cancers; however, the biological role and clinical significance of E2F8 in breast cancer remain to be further elucidated." (PMID 26992224, 2016). "Significantly, we found that E2F8 was upregulated and correlated with clinical progression and poor prognosis in human breast cancer." (PMID 26992224, 2016). "Since E2F8 is involved in the cell cycle regulation of breast cancer cells, we examined the expression of cell cycle regulators." (PMID 26992224, 2016). "Real-time PCR and western blotting revealed that E2F8, at both the mRNA and protein levels, was markedly overexpressed in all 11 tested breast cancer cell lines than that in normal breast epithelial cells (NBEC1 and NBEC2)." (PMID 26992224, 2016). "The functions of E2F8 on cell cycle progression and tumorigenesis in breast cancer are still unclear." (PMID 26992224, 2016). "Overexpressing E2F8 dramatically promoted, whereas silencing E2F8 inhibited the proliferation and tumorigenicity of breast cancer cells both in vitro and in vivo." (PMID 26992224, 2016). "Quantitative IHC analysis as determined by the mean optical density (MOD) showed that E2F8 expression increased along with disease stage in breast cancer (P < 0.05)." (PMID 26992224, 2016). "Herein, we report that E2F8 is robustly elevated in breast cancer cell lines and clinical breast cancer tissue samples, respectively." (PMID 26992224, 2016). "Since E2F8 expression was correlated with the clinical staging and TNM classification of breast cancer, we further evaluated the effect of E2F8 on the tumorigenic activity of breast cancer cells." (PMID 26992224, 2016). "In summary, our study has revealed that E2F8 upregulation plays an important role in breast cancer progression and E2F8 is a critical cell cycle promoter by directly upregulating CCNE1, and CCNE2." (PMID 26992224, 2016). "In the present study, we show that E2F8 is markedly upregulated in human breast cancer and closely correlates with the clinicopathological features and prognosis of breast cancer." (PMID 26992224, 2016). "First, we found that the anchorage-independent growth abilities of both MCF7 and SK-BR-3 breast cancer cell lines were significantly increased by overexpressing E2F8, but reduced by silencing E2F8." (PMID 26992224, 2016). "This study establishes a vital role for E2F8 as a promoter of breast cancer proliferation and tumorigenecity." (PMID 26992224, 2016). "Taken together, these results suggest that E2F8 promotes the tumorigenicity of breast cancer cells in vivo." (PMID 26992224, 2016). "E2F8 levels in 10 freshly collected breast cancer samples were significantly positively correlated with levels of cyclin E1 (r = 0.723, P = 0.018), cyclin E2 (r = 0.803, P = 0.005), and phosphorylation level of Rb (r = 0.639, P = 0.047)." (PMID 26992224, 2016). "Collectively, these results demonstrate that E2F8 can upregulate cyclin E1 and cyclin E2 in breast cancer by binding to the promoter of the CCNE1 and CCNE2 genes to activate their transcription." (PMID 26992224, 2016). "We then evaluated the role of E2F8 in breast cancer cell proliferation by stably exogenously overexpressing, or endogenously knocking down of E2F8 expression via retrovirus infection." (PMID 26992224, 2016). "In breast cancer, E2F8 was also evident to be related to the cell cycle signalling pathway." (PMID 39999286, 2025). "Furthermore, the TIMER database also revealed a positive correlation between E2F8 expression and ICMs in basal-like breast cancer." (PMID 36814821, 2023). "The results had shown that E2F8 was able to promote the cell cycle process, but it could inhibit the hormone ER pathway in all breast cancers using the GSCALite dataset." (PMID 36814821, 2023). "The expression of MYBL2, HOXC13, and E2F8 was verified by qRT-PCR assay in breast cancers." (PMID 36814821, 2023).
breast carcinoma (continued). "Furthermore, our data also showed that the upregulation of E2F8 was linked to higher enrichments of CD4+ and CD8+ T cells in breast cancers." (PMID 36814821, 2023). "In conclusion, our study showed that E2F8 could be a potential molecular biomarker for basal-like breast cancer." (PMID 36814821, 2023). "E2F8 functions as a tumor promoter in breast cancer by promoting cell proliferation." (PMID 35279688, 2022). "E2F7 and E2F8 have been reported to be involved in several malignancies such as pancreatic cancer, gallbladder cancer, colorectal cancer, cervical cancer, breast cancer and lung cancer." (PMID 34532281, 2021). "Furthermore, E2F transcription factors, from E2F1 to E2F8, have been reported as possible biomarkers for breast cancer, although their expression patterns and prognostic significance have been inconsistent in previous studies." (PMID 32650578, 2020). "Moreover, E2F8 expression has been found to be upregulated in ovarian cancer, hepatocellular cancer, lung cancer and breast cancer." (PMID 28270228, 2017). "Furthermore, E2F8 also promoted cancer malignant progression in breast cancer, prostate cancer and hepatocellular cancer, and served as a therapeutic target in lung cancer." (PMID 28270228, 2017). "Furthermore, our results reveal a potential molecular mechanism by which E2F8 promotes cell proliferation and tumorigenicity in breast cancer, via transcriptionally activating the CCNE1, and CCNE2 promoters." (PMID 26992224, 2016). "Moreover, the role of E2F8 in the tumorigenicity of breast cancer cells was further determined in vivo." (PMID 26992224, 2016). "Herein, we report that E2F8 upregulates cyclin E1 and cyclin E2 expression by directly binding to these genes promoters, further supporting the notion that E2F8 promotes breast cancer proliferation and tumorigenicity by upregulating multiple cell cycle regulators." (PMID 26992224, 2016). "The biological role of E2F8 in breast cancer was further explored using Gene Set Enrichment Analysis (GSEA) based on mRNA expression data from the TCGA, which indicated that high levels of E2F8 correlated significantly with proliferation-associated gene signature." (PMID 26992224, 2016). "Taken together, these findings provide strong evidence that upregulation of E2F8 plays important roles in promoting breast cancer progression, and E2F8 might represent a novel prognostic biomarker and therapeutic target for the disease." (PMID 26992224, 2016). "However, the clinical significance and biological role of E2F8 during the progression of breast cancer remain to be elucidated." (PMID 26992224, 2016). "The high expression level of E2F8 significantly correlates with clinical progression (P = 0.001), poor patient survival (P < 0.001) and a high Ki67 staining index (P = 0.008) in 187 human breast cancer specimens." (PMID 26992224, 2016). "Taken together, our findings indicate that E2F8 plays an important role in the progression of human breast cancer and suggest that E2F8 may be a potential target for human breast cancer treatment." (PMID 26992224, 2016). "Thus, our findings suggest that E2F8 contributes to the proliferation capabilities in different breast cancer subtypes." (PMID 26992224, 2016). "Furthermore, we find that overexpressing E2F8 promotes, whereas silencing E2F8 suppresses, the proliferation and tumorigenicity of breast cancer cells both in vitro and in vivo." (PMID 26992224, 2016). "Taken together, these findings uncover a novel biologic role and regulatory mechanism of E2F8 responsible for the progression of breast cancer, indicating E2F8 may represent a novel prognostic biomarker and therapeutic target against breast cancer." (PMID 26992224, 2016). "Furthermore, we verified E2F8 expression in breast cancer cell lines and fresh tissues." (PMID 26992224, 2016).
breast carcinoma (continued). "Interestingly, assessment from a publicly available breast cancer microarray data KM plotter has shown a significant correlation between high expression of E2F8 and poor overall survival, relapse-free survival and distant metastasis-free survival of breast cancer patients." (PMID 26992224, 2016). "However, the clinical significance and biological role of E2F8 in breast cancer remain largely unknown." (PMID 26992224, 2016). "Furthermore, we demonstrate that E2F8 can promote entry into the G1/S phase of the cell cycle via transcriptionally upregulating cyclin E1 and cyclin E2 expression, thus contributing to cell proliferation and tumorigenicity in human breast cancer." (PMID 26992224, 2016). "Moreover, E2F8 expression levels were positively correlated with Ki67 expression from both TCGA mRNA data set (r = 0.817, P < 0.001) and our IHC results (P < 0.001), suggesting that E2F8 may contribute to cell proliferation in breast cancer." (PMID 26992224, 2016). "Finally, we examined whether E2F8-mediated cyclin E1 and cyclin E2 activation in breast cancer cells was clinically relevant." (PMID 26992224, 2016). "Furthermore, the transwell assay showed that silencing of E2F8 dramatically reduced the invasion capability of basal-like breast cancer cells MDA-MB-231 and BT549, suggesting that E2F8 expression played an important role in the invasive phenotypes of basal-like breast cancer cells." (PMID 26992224, 2016). "Some of these biomarkers, including E2F8, TPX2 and CACNA1D, have been independently confirmed as tumourigenic or tumour-suppressive in breast cancer, and can thus point towards novel targets for treatment." (PMID 34131308, 2021). "Thus, it would be of great interest and importance to investigate whether E2F8 upregulates cyclin E1, and cyclin E2 expression induce proliferation and tumorigenesis in breast cancer via Rb-E2F pathway which is critical in regulating in initiation of DNA replication." (PMID 26992224, 2016). "An MTT assay showed that overexpression of E2F8 increased, while depletion of E2F8 expression reduced proliferation rates of both MCF7 and SK-BR-3 breast cancer cell lines." (PMID 26992224, 2016). "Similarly, the mRNA and protein levels of E2F8 were differentially upregulated in all 8 freshly-frozen breast cancer samples as compared to the matched adjacent non-tumor tissues, suggesting that E2F8 is upregulated in breast cancer cell lines and breast cancer tissues." (PMID 26992224, 2016). "As expected, luciferase reporter assays revealed that overexpression of E2F8 activated, whereas downregulation of E2F8 attenuated, the luciferase activity of CCNE1 and CCNE2 promoters in breast cancer cells in a dose-dependent manner." (PMID 26992224, 2016). "Understanding the precise role of E2F8 in breast cancer pathogenesis and in the cell cycle regulation promises to increase our knowledge of the biological basis of cancer development and may also facilitate the development of new therapeutic strategies against breast cancer." (PMID 26992224, 2016). "On the other hand, genes involved in breast cancer tumorigenesis such as CLAUDIN1 and E2F8 among others, were down-regulated after Bozepinib-treatment." (PMID 24946763, 2014). "Together, these results suggest that E2F7 and E2F8 may act as critical upstream transcriptional regulators of ESPL1, potentially promoting its overexpression in aggressive subtypes of breast cancer." (PMID 41268575, 2025). "Together, these findings implicate hsa-let-7b-5p as a critical post-transcriptional regulator of ESPL1 and highlight a potential ceRNA network involving hsa-let-7b-5p, E2F8, and ESPL1 that may drive tumor progression and poor prognosis in breast cancer." (PMID 41268575, 2025). "Additionally, we also observed that the up-regulation of E2F8 was accompanied with higher enrichments of CD4+ T cells and CD8+ T cells in breast cancers." (PMID 36814821, 2023).